NRIP2 (nuclear receptor interacting protein 2)
Description:
Down-regulates transcriptional activation by nuclear receptors such as NR1F2.
Synonyms: DKFZP761G1913; NIX1
Tractability: No criterion of Open Targets' tractability assessment is met for any kind of drug.
Gene: Protein-coding gene on chromosome 12 (2,825,348 to 2,835,544, reverse strand). Ensembl gene ENSG00000053702.
Subcellular location: Nucleus
Subcellular location (Human Protein Atlas): Cytosol; Nucleoplasm; Nuclear bodies
Gene Ontology:
Molecular function: protein binding; aspartic-type endopeptidase activity
Biological process: proteolysis
Cellular component: cytoplasm; nucleus
Genetic constraint (gnomAD): Loss-of-function variants: 27 observed, 36.04 expected, observed/expected ratio (o/e) 0.75, 90% interval 0.55 to 1.03. The upper end of that interval is the gene's LOEUF score, 1.03, which puts it in group 4 of 6, group 1 being the genes least tolerant of losing a copy. Missense variants: 385 observed, 368.69 expected, observed/expected ratio (o/e) 1.04, 90% interval 0.96 to 1.14. Synonymous variants: 145 observed, 154.99 expected, observed/expected ratio (o/e) 0.94, 90% interval 0.82 to 1.07.
Homologues: Orthologues: chimpanzee NRIP2 (99% identical), macaque NRIP2 (79% identical), dog NRIP2 (71% identical), mouse Nrip2 (67% identical), pig NRIP2 (66% identical), rat Nrip2 (65% identical), rabbit NRIP2 (63% identical), zebrafish nrip2 (40% identical), Drosophila melanogaster rngo (13% identical), Caenorhabditis elegans ddi-1 (11% identical). Paralogues in human: NRIP3 (33% identical), DDI2 (18% identical), DDI1 (17% identical), UBAC2 (14% identical).
Diseases named in the same sentence as NRIP2 in open-access papers:
NRIP2 is named in the same sentence as 8 diseases in open-access papers, as found by Europe PMC text mining. Sharing a sentence is not in itself a finding about the gene and the disease. The quoted sentences say what the papers report.
colorectal cancer (4 papers, 2017 to 2022). A primary or metastatic malignant neoplasm that affects the colon or rectum. "Right now, NRIP2 is upregulated in colorectal cancer initiating cells (CCIC) and mediates CCIC self-renewal via Wnt signaling." (PMID 35794546, 2022). "Nuclear receptor interacting protein 2 (NRIP2) modulates the Wnt pathway in colorectal cancer-initiating cells, but the role of NRIP2 in podocyte injury has not yet been investigated." (PMID 35004680, 2021). "Recently, NRIP2 was shown to regulate colorectal cancer-initiating cell renewal as a Wnt pathway interactor, functioning as a novel molecule that cooperates with RORβ and HMG box-containing protein 1 (HBP1) to modulate Wnt activity." (PMID 35004680, 2021). "In recent research, RORβ was a key target through which nuclear receptor-interacting protein 2 (NRIP2) regulated activity of the Wnt pathway in enriched colorectal cancer cells." (PMID 33336001, 2020). "NRIP2 overexpressed and knockdown colorectal cancer cells were produced to study the role of NRIP2 in Wnt pathway." (PMID 28137278, 2017). "NRIP2 was significantly up-regulated in CCICs from both cell lines and primary colorectal cancer tissues." (PMID 28137278, 2017). "Via retroviral library screening, we identified Nuclear Receptor-Interacting Protein 2 (NRIP2) as a novel interactor of the Wnt pathway from enriched colorectal cancer colosphere cells." (PMID 28137278, 2017). "Together, these findings suggested that NRIP2 involves in the self-renewal of colorectal cancer cells by activating the Wnt pathway." (PMID 28137278, 2017). "NRIP2 is a novel interactor of the Wnt pathway in colorectal cancer initiating cells." (PMID 28137278, 2017). "To verify that NRIP2 is expressed at a higher level in CCICs, we isolated CD44+CD24+ colorectal cancer-initiating cells from primary colorectal P1 and SW620 cells by fluorescence-activated cell sorting (FACS) and colospheres from colorectal cancer cell lines and primary colorectal cancer tissues." (PMID 28137278, 2017).
glomerulosclerosis (1 paper, 2021). A hardening of the kidney glomerulus caused by scarring of the blood vessels. "In ADR mice, genetic knockout of Nrip2 ameliorated podocyte injury and loss, glomerulosclerosis, and proteinuria by inhibiting β-catenin activation." (PMID 35004680, 2021).
Nephropathy (1 paper, 2021). A nonspecific term referring to disease or damage of the kidneys. "An adriamycin (ADR) nephropathy model was established in NRIP2 knockout mice." (PMID 35004680, 2021).
cancer (2 papers, 2017 to 2022). A tumor composed of atypical neoplastic, often pleomorphic cells that invade other tissues. "Among the six key PRSGs, NRIP2 and FDFT1 correlate with many cancer-associated TFs and hallmarks of cancer gene sets in the regulatory network." (PMID 35794546, 2022). "The model identified universal correlation between NRIP2 and FDFT1 (key PRSGs), and some cancer related transcription factors (TFs) and trademarks of cancer gene were in the regulatory network." (PMID 35794546, 2022). "NIX1 was found to participate in transcriptional repression in yeast cells, but the mechanism whereby NRIP2 regulates the Wnt activity and the self-renewal of cancer initiating cells has been rarely reported." (PMID 28137278, 2017).
tumor (1 paper, 2017). "The presence of NRIP2 in primary tumor cells was confirmed by mRNA fluorescence in situ hybridization (FISH) and immunohistochemical (IHC) staining." (PMID 28137278, 2017).
NRIP2 also shares sentences with these, for which no sentence is quoted: IgA nephropathy (1 paper); membranous nephropathy (1); minimal change disease (1).